Y_RNA (Y RNA )
Gene: Miscellaneous RNA gene on chromosome 18 (78,544,095 to 78,544,188, reverse strand). Ensembl gene ENSG00000201723.
Homologues: Orthologues: macaque Y_RNA (99% identical), chimpanzee Y_RNA (98% identical), guinea pig Y_RNA (81% identical). Paralogues in human: RNY4 (86% identical), RNY4P25 (85% identical), RNY4P7 (85% identical), RNY4P10 (84% identical), RNY4P19 (84% identical), RNY4P6 (84% identical), Y_RNA (84% identical), RNY4P24 (83% identical), Y_RNA (83% identical), RNY4P9 (82% identical), Y_RNA (82% identical), RNY4P13 (81% identical), and 88 more.